HOXD3 (homeobox D3)
Description:
Sequence-specific transcription factor which is part of a developmental regulatory system that provides cells with specific positional identities on the anterior-posterior axis.
Synonyms: HOX1D; HOX4A; HOX4; Hox-4.1
Tractability: PROTAC: ubiquitination databases record sites on it.
Gene: Protein-coding gene on chromosome 2 (176,136,545 to 176,174,227, forward strand). Ensembl gene ENSG00000128652.
Subcellular location: Nucleus
Subcellular location (Human Protein Atlas): Nucleoplasm; Nuclear bodies
Pathways (Reactome):
Developmental Biology: Activation of anterior HOX genes in hindbrain development during early embryogenesis
Gene Ontology:
Molecular function: DNA-binding transcription activator activity, RNA polymerase II-specific; protein binding; RNA polymerase II transcription regulatory region sequence-specific DNA binding; sequence-specific double-stranded DNA binding; DNA-binding transcription factor activity, RNA polymerase II-specific; RNA polymerase II cis-regulatory region sequence-specific DNA binding; DNA binding; DNA-binding transcription factor activity
Biological process: cell-matrix adhesion; DNA-templated transcription; Notch signaling pathway; positive regulation of gene expression; positive regulation of transcription by RNA polymerase II; anterior/posterior pattern specification; cartilage development; embryonic skeletal system morphogenesis; positive regulation of neuron differentiation; regulation of transcription by RNA polymerase II; thyroid gland development; regulation of DNA-templated transcription
Cellular component: nucleoplasm; chromatin; nucleus
Genetic constraint (gnomAD): Loss-of-function variants: 13 observed, 32.45 expected, observed/expected ratio (o/e) 0.4, 90% interval 0.26 to 0.64. The upper end of that interval is the gene's LOEUF score, 0.64, which puts it in group 2 of 6, group 1 being the genes least tolerant of losing a copy. Missense variants: 504 observed, 594.45 expected, observed/expected ratio (o/e) 0.85, 90% interval 0.79 to 0.91. Synonymous variants: 241 observed, 255.6 expected, observed/expected ratio (o/e) 0.94, 90% interval 0.85 to 1.05.
Homologues: Orthologues: chimpanzee HOXD3 (99% identical), macaque HOXD3 (99% identical), rabbit HOXD3 (98% identical), guinea pig HOXD3 (97% identical), pig HOXD3 (97% identical), dog HOXD3 (97% identical), rat Hoxd3 (97% identical), mouse Hoxd3 (96% identical), tropical clawed frog hoxd3 (68% identical), zebrafish hoxd3a (64% identical). Paralogues in human: HOXA3 (51% identical), HOXB3 (50% identical), HOXA2 (22% identical), HOXB2 (21% identical), PDX1 (20% identical), HOXD4 (18% identical), HOXA1 (18% identical), HOXC4 (17% identical), HOXB4 (17% identical), HOXB5 (16% identical), GSX2 (16% identical), HOXA4 (16% identical), and 30 more.
Diseases named in the same sentence as HOXD3 in open-access papers:
HOXD3 is named in the same sentence as 45 diseases in open-access papers, as found by Europe PMC text mining. Sharing a sentence is not in itself a finding about the gene and the disease. The quoted sentences say what the papers report.
lung carcinoma (10 papers, 2009 to 2024). "On three large public available lung cancer datasets, the key drivers ARHGDIB and HOXD3 demonstrated significant associations with the overall survival of lung cancer patients." (PMID 25802847, 2015). "For example, overexpression of homeobox gene HoxD3 induced an angiogenic phenotype and induced coordinate expression of metastasis-related genes in human lung cancer cells." (PMID 32784646, 2020). "In contrast, HOXD3 overexpression in lung cancer A549 cells transforms them from epithelial to mesenchymal morphology and causes a simultaneous reduction in E-cadherin expression levels and increase in α3 and β3 expression." (PMID 25136598, 2014). "HOXD3 promotes cell motile activity and invasiveness in lung cancer cells." (PMID 25136598, 2014). "Moriuchi group found that overexpression of the HOXD3 gene enhanced Integrin β3 expression in both human erythroleukaemia HEL cells and lung carcinoma A549 cells." (PMID 30823921, 2019). "Remarkably, HOXD3 gene, adjacent to HOXD-AS1 locus, has established role in promoting metastatic potential of lung cancer cells." (PMID 25522241, 2014). "Studies using the lung cancer cell line A549 and two melanoma cell lines (A375M, MMIV) suggest that overexpression of HOXD3 leads to increased motility and invasiveness in these cancers, and is not expressed in normal melanocytes." (PMID 19283074, 2009). "Six DMRs located on HOXA9, HOXD3, PCDH17, NID2, NPTX2, and SFRP2 genes exhibiting clinical accuracy over 75% irrespective of lung cancer subtype and cancer progression stages were selected as lung cancer-specific exosome DNA methylation biomarkers." (PMID 39123492, 2024).
prostate carcinoma (10 papers, 2009 to 2025). A carcinoma that arises from epithelial cells of the prostate gland. "Meantime, HOXD3 represented high methylation levels found in prostate cancer patients, which was associated with the recurrence of prostate cancer." (PMID 37827698, 2023). "Hypermethylation of HOXD3 has been associated with reduced expression and poor prognosis in OC and renal cancer and has demonstrated diagnostic potential using cfDNA in prostate cancer." (PMID 40563675, 2025). "For example, in our laboratory, transforming growth factor β 2 (TGFβ2) and homeobox D3 (HOXD3) hypermethylation has been discovered as potential biomarkers of prostate cancer progression through a genome-wide DMH screening." (PMID 23342273, 2012). "This technique has been previously used in our laboratory to provide accurate and quantitative methylation profiles of multiple CpGs in the Bone morphogenetic protein 7 (BMP7) and HOXD3 genes in prostate cancer samples." (PMID 23342273, 2012). "Besides, to our knowledge only HOXD3 has previously been described hyperM in cancer, specifically in prostate carcinoma." (PMID 23144874, 2012). "Further validation of candidate genes on a separate cohort of low and high grade prostate cancers by quantitative MethyLight analysis has allowed us to confirm DNA hypermethylation of HOXD3 and BMP7, two genes that may play a role in the development of high grade tumours." (PMID 19283074, 2009). "Furthermore, the involvement of particular HOX genes such as HOXC13, HOXD3, HOXA1 in metastasis and invasiveness was recently demonstrated for melanoma, breast and prostate cancer, respectively." (PMID 27363011, 2016). "Aberrant methylation of HOXD3 has not been described previously in NB, but has recently been reported as a novel biomarker of prostate cancer progression together with RASSF1A, TGF-β and APC." (PMID 23144874, 2012).
breast cancer (9 papers, 2016 to 2023). A primary or metastatic malignant neoplasm involving the breast. "Other studies observed that HOXD3 overexpression serves as an independent risk factor for poor prognosis of breast cancer." (PMID 32536823, 2020). "In breast cancer, for example, the expression of HOXD3 has been shown to be closely associated with integrin β3 expression." (PMID 29402992, 2018). "In breast cancer, the expression of HOXD3 was closely associated with Integrin β3 expression." (PMID 30823921, 2019). "The overexpression of HOXD3 increased breast cancer cell drug resistance through integrin β3-mediated Wnt/β-catenin signaling." (PMID 37827698, 2023). "In breast cancer, HOXD3 highly expressed and went through the integrin β3 to induce breast cancer cell stemness and drug resistance." (PMID 32557953, 2020). "Compared with normal breast tissue, HOXD3 was high-expressed in breast cancer tissue." (PMID 37827698, 2023). "Besides, some studies have demonstrated that OTOR, HOXD3, and PEG10 were associated with prognosis in breast cancer." (PMID 35950033, 2022). "Examples include HOXC6 in gastric cancer, HOXB8 in ovarian cancer, and HOXD3 in breast cancer." (PMID 26867567, 2016). "HOXD1, HOXD3, and HOXD4 were transcription factors and have been recognized as oncogenes in many cancers, such as liver cancer, gastric cancer, breast cancer, and as an inhibitor in kidney renal clear cell carcinoma." (PMID 37827698, 2023).
hepatocellular carcinoma (9 papers, 2016 to 2025). A malignant tumor that arises from hepatocytes. "For example, miRNA-99b-5p suppresses liver metastasis of colorectal cancer by down-regulating mTOR, and miR-203a suppresses cell metastasis and angiogenesis through VEGFR by targeting HOXD3 in human hepatocellular carcinoma cells." (PMID 29973668, 2018). "Activated miR-203a could suppress the hepatocellular carcinoma cells progression and induce the cell apoptosis by targeting HOXD3 through EGFR/AKT and ERK signaling pathway." (PMID 27244890, 2016). "Epigenetically, YY1 can recruit HDAC1 to form a repressor complex that downregulates HOXD3 expression, thereby suppressing the ITGA2 pathway in hepatocellular carcinoma cells." (PMID 40940943, 2025). "The effect of the HOXD3–CREBBP/Med15–CCL20–CCR6 axis on HCC migration and angiogenesis was further investigated, which could clarify a novel mechanism of action of HOXD3 in hepatocellular carcinoma." (PMID 38493218, 2024).
gastric cancer (6 papers, 2013 to 2025). A primary or metastatic malignant neoplasm involving the stomach. "Mechanistically, vitamin D receptor (VDR) – mediated miR-99b-3p targeted the HOXD3 to inhibit the proliferation of gastric cancer cells." (PMID 37827698, 2023). "Here, miR-99b-3p exerted an antiproliferative effect and arrested gastric cancer cells in the S phase of the cell cycle by inhibiting cell viability and targeting HoxD3, which is upregulated in GC cell lines." (PMID 36139227, 2022). "The expression of HOXD3, a member of the HOXD subfamily, is markedly increased in numerous cancers, such as HCC, gastric cancer (GC) and breast cancer." (PMID 38493218, 2024).
colorectal cancer (5 papers, 2018 to 2023). A primary or metastatic malignant neoplasm that affects the colon or rectum. "HOXD3 promotes the growth of colorectal cancer (CRC) cells and plays a key role in the development and survival of malignant human CRC cells." (PMID 36213580, 2022). "Similarly, HOXD-AS1 could recruit PRC2 to decrease the transcription of HOXD3, thus decreased the proliferation and migration of colorectal cancer." (PMID 35982032, 2022).
clear cell renal cell carcinoma (2 papers, 2019 to 2020). "For the survival analysis, we found that hypomethylation and over-expression of LAT and NFE2L3 were correlated with poor survival, while hypermethylation and low-expression HOXD3 was correlated with poor survival of clear cell renal cell carcinoma patients." (PMID 31777602, 2019). "Methylated hub genes, including HOXD3, LAT, and NFE2L3, were proved to be a novel prognostic indicators in clear cell renal cell carcinoma." (PMID 32296463, 2020).
colon carcinoma (2 papers, 2016 to 2018). "The inhibition of HOXD3 by shRNA in RKO cells significantly decreased proliferation and colony formation and increased apoptosis of RKO colon cancer cells." (PMID 30154863, 2018). "HOXD3 mRNA expression levels in hormone receptor-negative breast cancer are significantly higher than in non-cancerous tissues, whereas in colon carcinoma they are downregulated." (PMID 27244890, 2016).
glioma (2 papers, 2017 to 2023). A benign or malignant brain and spinal cord tumor that arises from glial cells (astrocytes, oligodendrocytes, ependymal cells). "Analysis of HOXD gene expression in human low-grade gliomas tissues revealed that HOXD1 and HOXD12 were highly expressed in gliomas, whereas the expression of HOXD3 was depressed." (PMID 29383189, 2017). "Another research examined the expression of HOXD family genes by QPCR in 14 pediatric low-grade gliomas and found that HOXD1 and HOXD12 were overexpressed in tumor tissue compared to non-neoplastic tissues, while HOXD3 presented lower expression in grade I glioma." (PMID 37547473, 2023).
liver cancer (2 papers, 2016 to 2023). An epithelial or non-epithelial malignant neoplasm that arises from the liver. "Similarly, expression of HOXD3 was previously demonstrated as associated with shorter survival time in patients with liver cancer." (PMID 37827698, 2023). "In this study, we used the TCGA database to test the expression of HOXD3 in liver cancer and normal tissues, and found that the expression of HOXD3 was increased in liver cancer tissues compared with their normal counterparts, which was consistent with our results." (PMID 27244890, 2016). "Moreover, in our previous research, we found that HOXD3 could target the promoter region of ITGA2 to induce liver cancer cell progression, invasion, metastasis, and angiogenesis." (PMID 37827698, 2023).
atherosclerosis (1 paper, 2020). A disease characterized by the build-up of fatty material and calcium deposition in the arterial wall resulting in partial or complete occlusion of the arterial lumen. "For example, HoxA9, HoxA10, and HoxD3 were expressed at higher levels in EC isolated from iliac arteries that are relatively protected from atherosclerosis compared to coronary arteries that are atherosusceptible." (PMID 31504243, 2020).
bladder urothelial carcinoma (1 paper, 2023). "Meanwhile, the association of HOXD1 expression with DFI was analyzed, and the results showed that high expression of HOXD1 induced poor DFI in KICH and PRAD (p < 0.01); HOXD3 in ACC, BLCA (bladder urothelial carcinoma), and PRAD (p < 0.01); HOXD4 in BLCA, ESCA, KICH, PCPG, and PRAD (p < 0.01)." (PMID 37827698, 2023).
breast tumours (1 paper, 2015). "However, it is worth noting that to our knowledge this is the first time that promoter methylation in CCDC8, HOXD3, PCDH8, PENK, STAT3, SFRP2 and WIFI has been described in primary breast tumours." (PMID 26052355, 2015).
chordoma (1 paper, 2023). Chordomas are rare malignant tumors arising from embryonic remnants of the notochord in axial skeleton. "Comparison of chordoma with NP showed DMRs in many cancer-related genes as well as in genomic cluster encoding homeobox domain genes (at HOXD3, HOXD4 and HOX11, HOXA9, HOXA10) that play an important role in both normal differentiation and tumorigenesis." (PMID 37434245, 2023). "Chordoma-specific DMRs were also found in location of homeobox domain genes (e.g. DMRs in HOXA4, HOXA5, HOXD3, HOXD4 MNX1, and NFIX) especially on chromosome 2 at HOXD cluster." (PMID 37434245, 2023).
Dyspareunia (1 paper, 2022). Recurrent or persistent genital pain associated with sexual intercourse. "We identified a HOXD3 missense variant in patient Fc-M-4, who was diagnosed with type I MRKH syndrome (ESHRE classification: U5bC4V4) with primary amenorrhea and dyspareunia." (PMID 35361250, 2022).
Glioblastoma multiforme (1 paper, 2023). "In the 33 types of cancers, the HOXD3 was increased in CHOL, DLBC, GBM (Glioblastoma multiforme), HNSC, LGG, LIHC, LUAD, LUSC (Lung squamous cell carcinoma), PAAD, PCPG (Pheochromocytoma and paraganglioma), SKCM, STAD, and THYM (p < 0.01)." (PMID 37827698, 2023).
hemangioma (1 paper, 2009). A benign vascular lesion characterized by the formation of capillary-sized or cavernous vascular channels. "In human hemangioma, expression levels of HoxD3 mRNA in the proliferation phase are higher than those in the involution phase." (PMID 19825192, 2009).
Hepatic fibrosis (1 paper, 2023). The presence of excessive fibrous connective tissue in the liver. "Fgfr3, Camk4, Gpx4, Hoxd3, and Prkcb were verified to be hyper-methylated in hepatic fibrosis of mice induced by CCl4 for 8 weeks." (PMID 36594057, 2023).
invasive breast carcinoma (1 paper, 2023). A carcinoma that infiltrates the breast parenchyma. "Moreover, Cheng reported that HOXD3 expression is a significant unfavorable prognostic factor and could serve as a potentially useful prognostic indicator for patients with invasive breast cancer." (PMID 37827698, 2023).
lymph node metastasis (1 paper, 2019). "The high expression of HOXD3 protein was positively associated with clinicopathologic features, including lymph node metastasis status, distant metastasis status, and poor outcome in CRC patients." (PMID 30823921, 2019).
neuroblastoma (1 paper, 2012). Neuroblastoma (NB) is the most common solid, extracranial childhood tumor. "Together, these findings demonstrate distinct functions of HOXD proteins in regulation of neuroblastoma cell proliferation, with only HOXD3, HOXD8, HOXD9, HOXD10 and HOXD12 proteins being able to recapitulate the G1 arrest phenotype induced by RA." (PMID 22879880, 2012).
osteosarcoma (1 paper, 2022). A usually aggressive malignant bone-forming mesenchymal neoplasm, predominantly affecting adolescents and young adults. "For example, lncRNA FOXC2-AS1 directly bound to FOXC2 mRNA and increased its expression to confer doxorubicin resistance in osteosarcoma, while lncRNA HOXD-AS1 mediated the recruitment of PRC2 to the HOXD3 promoter to significantly repress the transcription of the HOXD3 gene." (PMID 35986274, 2022).
prostate tumors (1 paper, 2018). "Increased methylation levels of HOXD3 and GSTP1 are observed in prostate tumors and are correlated with aggressive PCa and/or adverse clinical outcomes." (PMID 30470249, 2018).
serous ovarian cancer (1 paper, 2015). "Rs2857532 lies within intronic sequence of HOXD3, but does not coincide with enhancer marks in normal ovarian or fallopian cells, or in serous ovarian cancer cells." (PMID 26391404, 2015).